SLC8A3 (solute carrier family 8 member A3)
Description:
Mediates the electrogenic exchange of Ca(2+) against Na(+) ions across the cell membrane, and thereby contributes to the regulation of cytoplasmic Ca(2+) levels and Ca(2+)-dependent cellular processes. Contributes to cellular Ca(2+) homeostasis in excitable cells, both in muscle and in brain. In a first phase, voltage-gated channels mediate the rapid increase of cytoplasmic Ca(2+) levels due to release of Ca(2+) stores from the endoplasmic reticulum. SLC8A3 mediates the export of Ca(2+) from the cell during the next phase, so that cytoplasmic Ca(2+) levels rapidly return to baseline. Contributes to Ca(2+) transport during excitation-contraction coupling in muscle. In neurons, contributes to the rapid decrease of cytoplasmic Ca(2+) levels back to baseline after neuronal activation, and thereby contributes to modulate synaptic plasticity, learning and memory (By similarity). Required for normal oligodendrocyte differentiation and for normal myelination. Mediates Ca(2+) efflux from mitochondria and contributes to mitochondrial Ca(2+) ion homeostasis (By similarity).
Synonyms: NCX3
Tractability: Antibody: UniProt places it where antibodies can reach, with high confidence; its Gene Ontology location is reachable by antibodies, with high confidence; UniProt predicts a signal peptide or a membrane-spanning region. PROTAC: its protein half-life has been measured.
Gene: Protein-coding gene on chromosome 14 (70,044,215 to 70,189,480, reverse strand). Ensembl gene ENSG00000100678.
Subcellular location: Cell membrane; Perikaryon; Cell projection, dendrite; Cell projection, dendritic spine; Cell membrane, sarcolemma; Cytoplasm, sarcoplasm; Cell junction; Mitochondrion outer membrane; Cytoplasm, perinuclear region; Endoplasmic reticulum membrane
Subcellular location (Human Protein Atlas): Acrosome; Cytosol; End piece; Centrosome; Nucleoplasm
Pathways (Reactome):
Transport of small molecules: Mitochondrial calcium ion transport; Sodium/Calcium exchangers
Hemostasis: Reduction of cytosolic Ca++ levels
Muscle contraction: Ion homeostasis
Gene Ontology:
Molecular function: calcium:sodium antiporter activity; calcium:monoatomic cation antiporter activity; calcium:monoatomic cation antiporter activity involved in regulation of postsynaptic cytosolic calcium ion concentration
Biological process: calcium ion export across plasma membrane; calcium ion transmembrane transport; cellular response to hypoxia; intracellular calcium ion homeostasis; learning; learning or memory; long-term synaptic potentiation; memory; mitochondrial calcium ion homeostasis; mitochondrial calcium ion transmembrane transport; modulation of excitatory postsynaptic potential; myelination; negative regulation of intracellular signal transduction; oligodendrocyte differentiation; regulation of cardiac conduction; regulation of skeletal muscle contraction; sodium ion transmembrane transport; synapse organization; calcium ion import across plasma membrane; calcium ion transport; calcium ion transport into cytosol; cell communication; cellular response to cAMP; regulation of postsynaptic cytosolic calcium ion concentration; sodium ion transport; and 2 more
Cellular component: cytosol; perinuclear region of cytoplasm; plasma membrane; synapse; anchoring junction; axon; axon terminus; dendrite; endoplasmic reticulum membrane; mitochondrial outer membrane; neuromuscular junction; neuronal cell body; perikaryon; postsynapse; postsynaptic density; sarcolemma; dendritic spine; membrane; microtubule; postsynaptic membrane; sarcoplasm
Genetic constraint (gnomAD): Loss-of-function variants: 34 observed, 56.99 expected, observed/expected ratio (o/e) 0.6, 90% interval 0.45 to 0.79. The upper end of that interval is the gene's LOEUF score, 0.79, which puts it in group 3 of 6, group 1 being the genes least tolerant of losing a copy. Missense variants: 1,015 observed, 1,133 expected, observed/expected ratio (o/e) 0.9, 90% interval 0.85 to 0.94. Synonymous variants: 432 observed, 436.59 expected, observed/expected ratio (o/e) 0.99, 90% interval 0.91 to 1.07.
Homologues: Orthologues: chimpanzee SLC8A3 (100% identical), rabbit SLC8A3 (98% identical), macaque SLC8A3 (97% identical), pig SLC8A3 (97% identical), mouse Slc8a3 (95% identical), guinea pig SLC8A3 (95% identical), rat Slc8a3 (95% identical), dog SLC8A3 (93% identical), tropical clawed frog slc8a3 (86% identical), zebrafish slc8a3 (78% identical). Paralogues in human: SLC8A1 (71% identical), SLC8A2 (69% identical), ADGRV1 (31% identical), FREM2 (21% identical), FREM1 (17% identical), FRAS1 (17% identical), FREM3 (16% identical).
Diseases named in the same sentence as SLC8A3 in open-access papers:
SLC8A3 is named in the same sentence as 46 diseases in open-access papers, as found by Europe PMC text mining. Sharing a sentence is not in itself a finding about the gene and the disease. The quoted sentences say what the papers report.
brain ischemia (12 papers, 2014 to 2025). Diminished or absent blood supply to the brain caused by obstruction (thrombosis or embolism) of an artery resulting in neurologic damage. "Aberrant expression of SLC8A3 has been linked to disorders such as arrhythmia, cerebral ischemia, hypertension, heart failure, and diabetes, although its function in tumors has received less attention." (PMID 35518353, 2022).
Parkinson disease (5 papers, 2018 to 2025). A progressive degenerative disorder of the central nervous system characterized by loss of dopamine producing neurons in the substantia nigra and the presence of Lewy bodies in the substantia nigra and locus coeruleus. "In this context, SLC8A2 and SLC8A3 have even been proposed as new molecular targets in Parkinson’s disease and potential targets for therapeutic strategies." (PMID 32326436, 2020). "SLC8A3 and PMVK have been associated with bipolar disorder and Parkinson disease, respectively." (PMID 33314580, 2021).
atherosclerosis (1 paper, 2024). A disease characterized by the build-up of fatty material and calcium deposition in the arterial wall resulting in partial or complete occlusion of the arterial lumen. "The gene list included well-known atherosclerosis-associated genes Serpina3,42Cemip,43Thbs1,44Lum,45 and Spp146,47 but also novel genes without previous association to SMC function in atherosclerosis, such as Anxa4, Cd276, Itih4, Myof, Pcdh11x, Rab31, Serpinb6b, Slc35e4, Slc8a3, and Spink5." (PMID 38289873, 2024). "Moreover, we identified several novel genes not previously linked to SMCs in atherosclerosis, such as Anxa4, Cd276, inter-alpha-trypsin inhibitor-4 (Itih4), Myof, Pcdh11x, Rab31, Serpinb6b, Slc35e4, Slc8a3, and Spink5." (PMID 38289873, 2024).
colorectal cancer (1 paper, 2024). A primary or metastatic malignant neoplasm that affects the colon or rectum. "Finally, colorectal cancer cells migration, growth and colony formation assays were performed in RKO cells with the overexpression or knockdown SLC8A3, SLC24A2, SLC24A3, or SLC24A4." (PMID 39006025, 2024). "Finally, our study identified two previously unreported model genes (SLC8A3 and SLC24A4) that contribute to the growth and migration of colorectal cancer RKO cells." (PMID 39006025, 2024).
ischemia reperfusion injury (1 paper, 2022). Adverse functional, metabolic, or structural changes in ischemic tissues resulting from the restoration of blood flow to the tissue (reperfusion), including swelling; hemorrhage; necrosis; and damage from free radicals. "According to Chen’s study, SLC8A3 can protect myocardial cells against ischemia reperfusion injury in rats." (PMID 36253874, 2022).
keratoconus (1 paper, 2023). A degenerative, structural disorder of the eye, characterized by a cone-shaped protrusion of the cornea. "The presence of mutations in SLC8A3 appears to lead to an affected stroma; given the importance of the involvement of this corneal layer in the etiology studied, this gene is speculated as a possible causal gene for keratoconus." (PMID 37895187, 2023).
lung carcinoma (1 paper, 2025). "Therefore, the molecular mechanisms underlying the role of SLC8A3 in lung cancer remain unclear." (PMID 40610422, 2025). "However, no studies have confirmed whether SLC8A3 interacts with other proteins to affect the development of lung cancer." (PMID 40610422, 2025).
lung squamous cell carcinoma (1 paper, 2025). "In TIMM23-knockdown human embryonic kidney 293 T (HEK293T) cells, undegraded PINK1 accumulated, whereas TIMM23 expression remained unchanged in lung squamous cell carcinoma cell lines H226 and H520 despite variations in BRF2 and SLC8A3 levels." (PMID 40610422, 2025).
melanoma (1 paper, 2020). A malignant, usually aggressive tumor composed of atypical, neoplastic melanocytes. "We also identified mutations in three genes (SLC9A2, CASR, SLC8A3) never reported in melanoma, which might deserve further investigations." (PMID 32241263, 2020).
neurotoxicity (1 paper, 2022). Toxicity that causes injury to the central or peripheral nervous system or damages its function. "The third module included 3 genes in Neurotoxicity (Itpr1, Trim8, Lrp1), 4 in Blood–brain barrier (Ptpn23, Claudin5, Plectin, Mmp2) and 4 in Cognitive function (Slc8a3, Srf, Nf1, Ncam1)." (PMID 35899365, 2022).
osteosarcoma (1 paper, 2022). A usually aggressive malignant bone-forming mesenchymal neoplasm, predominantly affecting adolescents and young adults. "Account for the prognostic value of SLC8A3 in osteosarcoma, further experiments should be conducted to explore its role in osteosarcoma." (PMID 35518353, 2022).
Schnyder corneal dystrophy (1 paper, 2023). Schnyder corneal dystrophy (SCD) is a rare form of stromal corneal dystrophy characterized by corneal clouding or crystals within the corneal stroma, and a progressive decrease in visual acuity. "SLC8A3 is associated with Schnyder’s corneal dystrophy (MIM: #121800), which is a rare autosomal dominant disease characterized by the abnormal deposition of collagen and phospholipids in the corneal stroma that is associated with decreased visual acuity." (PMID 37895187, 2023).
squamous carcinoma (1 paper, 2025). "BRF2 expression was upregulated in squamous carcinoma cells, which increased SLC8A3 protein expression, promoted mitochondrial autophagy, stabilized MMP, and reduced apoptosis." (PMID 40610422, 2025).
cancer (4 papers, 2017 to 2024). A tumor composed of atypical neoplastic, often pleomorphic cells that invade other tissues. "For example, AGTR1, GRIN2A, ITPKB, and SLC8A3 were repressed by hypermethylation in six cancer types, and ADCY4, ADCY8, BST1, and PRKCB were inhibited by hypermethylation in five cancer types." (PMID 28060724, 2017). "The association of SLC8A3, SLC24A2, SLC24A3 and SLC24A4 with cancer is still unknown." (PMID 39006025, 2024). "Alterations in the Ca2+ signaling pathway were observed in nine cancer types and AGTR1 GRIN2A (Glutamate Ionotropic Receptor NMDA Type Subunit 2A), ITPKB (Inositol-Trisphosphate 3-Kinase B), and SLC8A3 (Solute Carrier Family 8 Member A3) were repressed by hypermethylation in six of them." (PMID 32629766, 2020).
tumor (4 papers, 2020 to 2025). "The in vivo rescue experiments demonstrated that overexpression of SLC8A3 effectively restored the impaired tumor growth rate, volume, and weight in BRF2 knockout nude mice." (PMID 40610422, 2025). "Additionally, TUNEL staining revealed that SLC8A3 expression counteracted the effects of BRF2 knockout on tumor cell apoptosis in nude mice." (PMID 40610422, 2025). "Therefore, rescue experiments were performed by overexpressing SLC8A3 in BRF2 knockout cells to determine whether SLC8A3 is involved in the effect of BRF2 on tumor apoptosis." (PMID 40610422, 2025). "It is imperative and rational to explore the function and mechanisms of these potential signature genes (SLC8A3 and SLC24A4) in CRC progression using experimental animal models and tumor cells derived from patients in future studies." (PMID 39006025, 2024). "Altogether, these results suggest that SLC8A3 and SLC24A4 may be involved in CRC growth and metastasis as tumor suppressor genes." (PMID 39006025, 2024).
SLC8A3 also shares sentences with these, for which no sentence is quoted: Alzheimer disease (8 papers); Cerebral ischemia (5); Stroke (5); neurological diseases (4); cognitive deficits (3); ischemia (3); neurodegenerative disease (3); bipolar disorder (2); colon cancer (2); glioblastoma (2); insomnia (2); multiple sclerosis (2); ovarian carcinoma (2); amyloidosis (1); amyotrophic lateral sclerosis (1); Arrhythmia (1); autosomal dominant disease (1); cardiac hypertrophy (1); cognitive decline (1); diabetes (1); heart disease (1); heart failure (1); HIV-1 infection (1); Hypertension (1); hypoxic-ischemic encephalopathy (1); infarction (1); lymph node metastasis (1); medulloblastoma (1); spinal muscular atrophy (1); status epilepticus (1).
A further 1 disease shares a sentence with SLC8A3 in 1 paper.